MYCN (MYCN proto-oncogene, bHLH transcription factor)
Diseases named in the same sentence as MYCN in open-access papers (continued):
Sharing a sentence is not in itself a finding about the gene and the disease.
neuroblastoma (continued). "MYCN amplification, identified in up to 30% of neuroblastomas, is a powerful and reliable marker of aggressive disease and is strongly prognostic of poor outcome." (PMID 23181218, 2012). "Summary of studies which have observed an inverse relationship between DKK3 expression and MYCN expression and/or MYCN amplification in neuroblastoma." (PMID 23226679, 2012). "The MYCN oncogene plays an important role for neuroblastoma development, tumor aggressiveness and clinical prognosis." (PMID 23284678, 2012). "The EP2 receptor has previously been shown to be epigenetically silenced in preferentially MYCN-amplified neuroblastoma tumors and cell lines, and therefore suggested to act as a tumor suppressor in aggressive neuroblastomas." (PMID 22276108, 2012). "Galectin-3 is broadly expressed in human neuroblastoma cell lines and tumors and is repressed by MYCN to induce the apoptosis-sensitive phenotype." (PMID 23152863, 2012). "Low levels of CHD5 expression have been found in neuroblastoma cell lines, as well as correlating with MYCN amplification and poor prognosis in neuroblastoma tumors." (PMID 23226679, 2012). "In support of this, studies in neuroblastoma have observed that MYCN functionally cooperates with Twist-1 or BMI-1 to induce neuroblastoma tumorigenesis, where overexpression of Twist-1 or BMI-1 is necessary for tumor growth both in vitro and in vivo." (PMID 23226679, 2012). "HIPK2 is largely expressed in human primary MYCN amplification (MNA) neuroblastoma tissues and its expression is induced by MYCN, whose inactivation inhibits HIPK2 and impairs p53Ser46 phosphorylation and apoptosis." (PMID 22889244, 2012). "Recently, we described a strategy for developing tumor cell specific PCRs for MYCN amplified neuroblastomas, using junction sites (amplicon fusion sites, AFS) of amplified genomic regions (ampGR) as template (AFS-PCR)." (PMID 23210797, 2012). "Consistent with this, overexpression of DKK3 inhibited the proliferation of MYCN amplified neuroblastoma cell lines in vitro." (PMID 23226679, 2012). "The widespread deregulation of miRNAs in neuroblastoma is reported to be due to MYCN amplification and chromosomal imbalances." (PMID 23226679, 2012).
neuroblastoma (continued). "This paradox is observed histologically by a high mitosis-karyorrhexis index, a combined index of both proliferation and apoptosis, in both human MYCN amplified neuroblastoma tumors and TH-MYCN transgenic mouse neuroblastoma tumors." (PMID 23226679, 2012). "Supporting its pivotal biological role in neuroblastoma, MYCN overexpression in the neural crest is sufficient to promote the development of neuroblastic tumors in transgenic mice." (PMID 23091802, 2012). "The PKM2 splicing switch and PTBP1 expression upregulation we found in stage 4+ neuroblastoma suggest a MYCN-controlled pathway for PKM2 splicing in neuroblastoma." (PMID 21501490, 2011). "Our current study indicates, for the first time, that MYCN amplification is not only related to large scale gene expression changes but also profound splicing regulation in neuroblastoma." (PMID 21501490, 2011). "In summary, we were able to define a subset of miRNA that are able to regulate MYCN expression when overexpressed in MNA neuroblastoma cells." (PMID 21654684, 2011). "Overall, our results in the mouse model indicate that the over-expression of MYCN strongly deregulates miRNAs expression, similar to the situation in human neuroblastoma." (PMID 22164278, 2011). "These miRNAs were able to suppress endogenous N-myc protein in a MYCN-amplified neuroblastoma cell line." (PMID 21654684, 2011). "Further evidence that this transcription factor directly contributes to tumorigenesis is provided by the development of neuroblastoma-like tumors in a transgenic mouse model over-expressing MYCN." (PMID 21731748, 2011). "TH-MYCN transgenic mice with the MYCN oncogene in the germline, driven by the tyrosine hydroxylase (TH) promoter, develop a tumour phenotype which closely resembles human neuroblastoma." (PMID 21698133, 2011). "We reveal that MNA neuroblastoma cell lines induced to express the anti-MYCN shRNAs efficiently undergo morphological and biochemical changes consistent with neuronal differentiation." (PMID 21194500, 2011). "Most results dealing with miRNA in neuroblastoma concern the identification of miRNAs differentially expressed in MYCN-amplified vs non-MYCN-amplified tumours." (PMID 21970883, 2011). "MYCN is well-known to be amplified in Stage IV neuroblastoma, and children with highly amplified MYCN suffer aggressive, poor prognosis disease." (PMID 22039435, 2011). "We have developed an efficient MYCN-knockdown in vitro model system to study neuronal differentiation in MNA neuroblastomas." (PMID 21194500, 2011). "In summary, our study demonstrated the important roles of splicing regulation in high-stage and MYCN amplified neuroblastoma." (PMID 21501490, 2011). "MYCN-amplified tumor is a highly aggressive subtype with poor prognosis in 20% of neuroblastoma patients." (PMID 21501490, 2011). "We previously reported that MYCN co-localizes to regions of hypermethylated DNA in neuroblastoma cell lines at a significantly higher than expected frequency." (PMID 21731748, 2011). "TH-MYCN is a well-characterized transgenic model of MYCN-driven neuroblastoma which recapitulates many clinicopathologic features of the human disease." (PMID 22164278, 2011). "Despite intense efforts to elucidate a mechanism by which MYCN overexpression acts to promote the aggressive phenotype, the functional roles of the MYCN protein in neuroblastoma are poorly understood." (PMID 21194500, 2011). "In this study we use retrovirally delivered inducible short-hairpin RNA (shRNA) modules to knock down MYCN expression in MYCN-amplified (MNA) neuroblastoma cell lines." (PMID 21194500, 2011).
neuroblastoma (continued). "To investigate the functional role of MYCN-targeting miRNAs in MNA neuroblastoma, we continuously monitored the proliferation of Kelly cells after transfection with miRNA mimics." (PMID 21654684, 2011). "Here, we have investigated how microRNAs (miRNAs) contribute to the control of MYCN expression in MNA neuroblastoma cells." (PMID 21654684, 2011). "High level amplification of MYCN occurs in multiple pediatric cancers, and for neuroblastoma it is the most important genetic prognostic indicator of poor clinical outcome." (PMID 21731748, 2011). "Our results suggested a significant role of splicing regulation in high stage and MYCN amplified neuroblastoma tumors." (PMID 21501490, 2011). "In this study, we have developed a retroviral tetracycline-inducible anti-MYCN shRNA expression system to study MYCN knockdown-mediated neuronal differentiation in MNA neuroblastoma cell lines." (PMID 21194500, 2011). "To study the role of splicing regulation in high stage and MYCN amplified neuroblastoma, we used HuEx array to measure exon expression levels in 47 neuroblastoma samples from 10 stage 1-, 28 stage 4-, and 9 stage 4+ tumors." (PMID 21501490, 2011). "In this study, we used exon array profiling to investigate global alternative splicing pattern of 47 neuroblastoma samples in stage 1 and stage 4 with normal or amplified MYCN copy number (stage 1-, 4- and 4+)." (PMID 21501490, 2011). "The tumour-suppressor miRNAs let-7 and mir-101 target MYCN and inhibit proliferation and clonogenic growth of MYCN-amplified neuroblastoma cells." (PMID 21654684, 2011). "In this study, we identified candidate genes undergoing splicing disruption in high stage and MYCN amplified neuroblastoma, which help the understanding of disease biology." (PMID 21501490, 2011). "Amplification of MYCN is detected in 20-30% of neuroblastomas and is the most important genetic aberration in this disease, strongly related to poor outcome." (PMID 21304178, 2010). "We then went on to show that B-MYB expression is selectively required for proliferation of MYCN amplified tumours unveiling a reciprocal regulatory loop of the two transcription factors in neuroblastoma." (PMID 21304178, 2010). "Risk assessment in neuroblastoma is based upon a number of factors which include, among others, age at diagnosis, International Neuroblastoma Staging System (INSS) stage, and MYCN status." (PMID 20624283, 2010). "The most well known genetic alteration in neuroblastoma is the amplification of the MYC-related oncogene (MYCN), which is still the only prognostically significant oncogene amplification in neuroblastoma." (PMID 20444257, 2010). "MYCNOS and SLC30A3 were confirmed to be correlated with the status of expression of MYCN in neuroblastoma." (PMID 20380745, 2010). "In 1983 Schwab and colleagues identified a MYC-related oncogene, named MYCN, that was amplified in a panel of neuroblastoma cell lines." (PMID 21304178, 2010). "In this study, we monitored the expression of B-MYB and MYCN in multiple microarray experiments containing data from hundreds of neuroblastoma patients." (PMID 21304178, 2010). "There are several cyctogenetic aberrations in neuroblastoma but, by far, the most clinically relevant is the amplification of MYCN." (PMID 21304178, 2010). "Inhibition of MYCN by antisense or RNA interference approaches decreases the G1-S transition of the cell cycle or induces apoptosis in MYCN amplified neuroblastoma cells in culture." (PMID 21304178, 2010). "This oncogenic transcription factor is responsible for the dysregulation of numerous genes and genetic pathways in neuroblastoma, and more recently it has become apparent that MYCN is also responsible for the dysregulation of microRNA." (PMID 20409325, 2010).
neuroblastoma (continued). "Only 1 out of 14 (7%) 12q24.31-gained neuroblastomas showed concomitant MYCN amplification, which was detected in altogether 7 neuroblastoma cases." (PMID 20444257, 2010). "Notable examples include HER2 amplification in breast cancer, EGFR amplification in lung cancer, and MYCN amplification in neuroblastoma." (PMID 20569491, 2010). "This analysis revealed that B-MYB is significantly co-expressed with MYCN in neuroblastoma patients and in the follow-up experiments we show that MYCN and B-MYB regulate each other with important biological consequences." (PMID 21304178, 2010). "Using multiple in silico databases we show that expression of B-MYB significantly correlates with that of MYCN in neuroblastoma patients." (PMID 21304178, 2010). "Despite the importance of MYCN amplification in neuroblastoma, little work has been done to examine the transcriptional regulation of the MYCN amplicon." (PMID 21304174, 2010). "Lastly, B-MYB was also shown to bind to the MYCN promoter in chromatin-IP assays of MYCN amplified neuroblastoma cells in culture, and induced a relatively modest transcriptional upregulation of a MYCN promoter element." (PMID 21304174, 2010). "This study identifies AKT2 as an important pro-survival gene in neuroblastoma and our results further demonstrate that MYCN indirectly regulates AKT2 through miR-184." (PMID 20409325, 2010). "As expected, neuroblastoma cell lines with amplification of MYCN also over-express B-MYB, validating the microarray data." (PMID 21304178, 2010). "Nuclear staining of B-MYB was frequently detected (54% of samples) in neuroblastomas and expression was particularly strong in MYCN amplified cases." (PMID 21304178, 2010). "Patients without MYCN or 12q24.31 amplification had the best prognosis, patients with the gain of 12q24.31 region had an intermediate prognosis, and patients with MYCN-amplified neuroblastomas had the worst prognosis." (PMID 20444257, 2010). "In order to experimentally determine that MYCN levels influence quantities of miR-184, we examined miR-184 expression in the SH-EP TET21 neuroblastoma cell line containing a MYCN construct which is repressible by doxycycline." (PMID 20409325, 2010). "MYCN is a well studied oncogene known to be amplified in neuroblastoma and in a subset of RB tumors." (PMID 20461151, 2010). "We observed a 1.56- to 2.38-fold increase in B-MYB expression levels after MYCN transfection, Secondly, we used a neuroblastoma cell line containing a construct conditionally activating MYCN in the presence of 4-hydroxytamoxifen." (PMID 21304178, 2010). "A similar increase in PC has been shown to be related to the expression of the MYCN oncogene in neuroblastoma, which are histologically very similar to medulloblastoma." (PMID 20842126, 2010). "MYCN amplification appears mostly with isochromosome 17 in Medulloblastoma, but only with 17q amplification in Neuroblastoma—rarely with whole chromosome gain." (PMID 19352461, 2009). "MYCN-amplified human neuroblastoma cells (IMR-32, 2 × 106) were injected into the left adrenal gland in SCID mice through a flank incision." (PMID 19284605, 2009). "Gene amplification is the major mechanism of oncogenesis for a number of cancer genes, including MYCN, which is amplified in ∼ 30% of advanced neuroblastomas." (PMID 19285540, 2009). "Our results indicate that amplification of the MYCN transcription factor has significantly affected miRNA expression in neuroblastoma tumors, consistent with our earlier observations and the observations of other groups." (PMID 19924232, 2009). "Using three MYCN single copy (MNS) and three MYCN amplified (MNA) neuroblastoma cell lines, we first measured the expression of 10 known differentially expressed genes (MYCN itself and nine known MYCN regulated genes) before and after pre-amplification." (PMID 19930725, 2009).
neuroblastoma (continued). "This oncogenic role was later confirmed using MYCN-transgenic mice: targeted expression of MYCN to neural crest-derived cells under the control of the Tyrosine Hydroxylase promoter leads to the development of neuroblastoma-like tumours in all homozygous mice." (PMID 20017904, 2009). "The expression of the oncodevelopmental antigen polySia and its main carrier NCAM was compared with the age, stage, MYCN-amplification status, histology according to the International Neuroblastoma Pathology Classification (INPC) and proliferation index (PI)." (PMID 19222860, 2009). "The TH-MYCN transgenic mouse is the most widely used murine model of human neuroblastoma, in which a human MYCN oncogene is targeted to neuroectodermal cells of developing mice under the influence of the rat tyrosine hydroxylase promoter." (PMID 19730731, 2009). "Current prognostic evaluations are based on clinical stage, age and MYCN amplification in neuroblastoma." (PMID 19222860, 2009). "We observed clonal growth in serum-free neurosphere media in four of eight neuroblastoma cells lines tested, which correlated with their MYCN amplification status." (PMID 19156211, 2009). "In another study, analysis of gene expression profiles of neuroblastomas identified coordination between high MYCN levels and high levels of another oncogene, H-Twist, that functions to antagonize MYCN's proapoptotic effects." (PMID 19690609, 2009). "High level genomic amplification of the MYCN gene occurs in approximately 20 to 25% of neuroblastoma (NB), a highly genetically heterogeneous childhood cancer derived from precursor cells of the sympathetic nervous system." (PMID 19997598, 2009). "All patients with MYCN-amplified neuroblastomas (seven patients) had stage 4 disease (i.e. distant metastases) at diagnosis." (PMID 19222860, 2009). "Serum RASSF1A methylation was more frequently detected in neuroblastoma patients with age ⩾12 months at diagnosis (P=0.002), stage 4 (P<0.001) and MYCN amplification (P<0.001)." (PMID 19165202, 2009). "Amplification of the MYCN gene in neuroblastoma (NB) is associated with a poor prognosis." (PMID 19615087, 2009). "In single copy MYCN (SCN) neuroblastoma cell lines, MYCN has also been demonstrated to enhance proliferation after bFGF administration." (PMID 20017904, 2009). "It should be noted that we found significantly higher GATA-4 expression levels in the unfavourable subgroups of MYCN-amplified tumours and of neuroblastoma with unfavourable PAM prediction." (PMID 19707195, 2009). "The MYCN oncogene was originally identified due to its frequent amplification and over expression in certain tumours, chiefly human neuroblastoma." (PMID 19997598, 2009). "There are circumstances where both hemizygous and homozygous transgenic mice are necessary to explore the role of MYCN in neuroblastomas." (PMID 19730731, 2009). "Tissue specific conditional mycn knockout in neural progenitor cells during mouse development has demonstrated the importance of mycn for regulating neurogenesis, perhaps explaining the greater role of MYCN in neuroblastoma pathogenesis over c-MYC." (PMID 19997598, 2009). "Taken together, GATA-4 expression appears to be a common feature of neuroblastoma with highest expression levels in MYCN-amplified tumours." (PMID 19707195, 2009). "To further validate target gene regulation by MYCN/c-MYC in neuroblastoma cells, we performed ChIP-chip using a 244K oligonucleotide promoter microarray (Agilent)." (PMID 18851746, 2008). "In vitro or in vivo treatment with antagomir-17-5p abolishes the growth of MYCN-amplified and therapy-resistant neuroblastoma through p21 and BIM upmodulation, leading to cell cycling blockade and activation of apoptosis, respectively." (PMID 18493594, 2008). "Altogether, these results demonstrate that in vivo treatment of MYCN-amplified neuroblastoma with antagomir-17-5p abolishes tumor growth by upmodulation of p21 and BIM and increased apoptosis." (PMID 18493594, 2008).